CYBB (cytochrome b-245 beta chain)
Diseases named in the same sentence as CYBB in open-access papers (continued):
Sharing a sentence is not in itself a finding about the gene and the disease.
tumor (continued). "Furthermore, FRGs, IRGs, DEGs, and genes in the blue module were intersected, and seven hub genes (JUN, TNFAIP3, NOX4, HMOX1, SOCS1, CYBB, and TFRC), related to both ferroptosis and tumor immunity, were obtained." (PMID 35174170, 2021). "Finally, we isolated the CD15+ cells and CD4/CD8pos T cells at 24 h from APCCs and analyzed the expression of key immune‐suppressive genes of MDSCs (ARG1, NCF1, NCF4, CYBB) which mediate MDSC arginase 1 secretion and NO generation to inhibit T cells within the tumor TME." (PMID 35611994, 2022). "Among them, CYBB, ITGAM, and PLEK showed significantly negative correlations with tumor purity (ρ = -0.555, -0.514, and -0.44), suggesting their potential as markers of the immune microenvironment." (PMID 40895569, 2025). "A number of interferon-stimulated genes (ISGs) were found to be highly induced in tumor compared to non-tumor samples, such as GBP1, CAMP, PTGS2, GOLIM4, IFIT3, MX1, LTF, and CYBB." (PMID 34400640, 2021). "Unlike the case in these BA-relapsed patients, TIGIT did not appear to be expressed in MCL tumor cells in the BA-refractory patient (R); in contrast, elevated expression of other checkpoint molecules, LAGLS9 and CYBB, was detected in MCL tumor cells from patient R." (PMID 36163179, 2022).
cancer (79 papers, 2007 to 2025). A tumor composed of atypical neoplastic, often pleomorphic cells that invade other tissues. "However, our findings indicated that CYBB might physically interact with Nrf2 to promote its subsequent upregulation, thus causing mesenchymal shift, cancer stemness, and TMZ resistance in GBM." (PMID 37175412, 2023). "The findings indicate that the molecular interaction of CYBB with Nrf2 led to a shift in the mesenchymal phenotype, cancer stemness promotion, and resistance development in GBM." (PMID 37175412, 2023). "Therefore, TMZ resistance in mesenchymal GBM was associated with aberrant CYBB expression, Nrf2/SOD2 mitochondrial antioxidant axis activation, and cancer stemness properties." (PMID 37175412, 2023). "CYBB, CYBA, NCF1, NCF2, and RAC2 are NADPH oxidase (NOX) subunit genes and are associated with inflammation and fibrosis in multiple organs, such as the liver, lungs, and kidneys, as well as with various types of cancer." (PMID 37109526, 2023). "Interestingly, NOX2 (encoded by CYBB) seems to have similar, although less striking, correlation patterns to NOX4 with all the cancer progression-related markers we surveyed." (PMID 33557266, 2021). "The bar charts show the total alteration frequency of six hub genes (CD36, CXCL12, CXCR4, CYBB, ITGAM, PLEK) in pan-cancer." (PMID 40895569, 2025). "We performed intersection analysis between NACDGs and found that CYBB and CA9 are shared among all cancer datasets." (PMID 33670487, 2021). "As revealed by IHC staining analysis, the proteins of CYBB, IL1A, IL1B, and SLC25A5 were mainly found in cancer cells’ nucleus, cytoplasm, and membranes; brown staining indicated positive staining; and these NRG proteins were either weakly expressed or not expressed in normal tissues." (PMID 36253777, 2022). "The transcripts included in the final signature were BCL10, CXCL11, CYBB and GBP1 and, based on their expression levels, our algorithm was able to classify plasma samples into cancer and control with a receiver operating characteristic (ROC) area under the curve (AUC) of 0.92 to 0.95." (PMID 33580122, 2021). "Western blotting results revealed that TMZ-resistant U87MG-R cells highly expressed CYBB along with Nrf2, SOD2, and other epithelial–mesenchymal transition (EMT) markers, such as slug, vimentin, N-Cadherin, and CD44, in addition to the upregulation of cancer stemness marker CD133." (PMID 37175412, 2023).
neurodegenerative disease (37 papers, 2011 to 2025). A disorder of the central nervous system characterized by gradual and progressive loss of neural tissue and neurologic function. "CYBB (also called NOX2), catalyzes the formation of ROS and was thought to be a new drug target and biomarker in neurodegenerative diseases." (PMID 35873477, 2022).
cardiovascular disease (31 papers, 2015 to 2025). "CYBB, also known as NOX2, has been implicated in oxidative stress in various cardiovascular diseases." (PMID 35305619, 2022).
metabolic disease (5 papers, 2020 to 2025). A congenital disorder (due to inherited enzyme abnormality) or acquired (due to failure of a metabolically important organ) disorder resulting from an abnormal metabolic process. "These additional putative mono/oligogenic SLE genes are involved in type I IFN regulation (DDX58, NLRC4 and PACSIN1), disruption of B cell and T cell tolerance (DOCK8, FAS and LRBA) and metabolic disorders (CYBB, MAN2B1, SLC7A7)." (PMID 40386946, 2025).
infectious disease (4 papers, 2017 to 2023). A disorder directly resulting from the presence and activity of a microbial, viral, or parasitic agent in humans. "The CYBB gene is located at chromosome X. According to the DisGeNET database, polymorphisms in the CYBB gene have been the subject for genetic association studies in hematological and infectious diseases." (PMID 36902173, 2023).
CYBB also shares sentences with these, for which no sentence is quoted: endothelial dysfunction (126 papers); Stroke (57); heart failure (42); myocardial infarction (41); Cognitive impairment (32); ischemia (29); Cerebral ischemia (28); injury (23); liver fibrosis (23); Parkinson disease (23); Alzheimer disease (20); cardiomyopathy (19); Arthritis (18); bacterial infection (18); leukemia (18); breast carcinoma (17); Hepatic steatosis (17); viral infection (17); diabetic retinopathy (16); neurological diseases (16); brain injury (14); Hypercholesterolemia (14); inflammation (14); influenza (14); prostate carcinoma (14); pulmonary fibrosis (12); rheumatoid arthritis (12); fibrosis (11); pneumonia (11); depression (10).
A further 345 diseases each share a sentence with CYBB in 10 papers or fewer.